R3HDM4 (R3H domain containing 4)
Synonyms: C19orf22; MGC16353
Tractability: PROTAC: ubiquitination databases record sites on it.
Gene: Protein-coding gene on chromosome 19 (896,503 to 913,245, reverse strand). Ensembl gene ENSG00000198858.
Subcellular location: Nucleus
Subcellular location (Human Protein Atlas): Nucleoplasm; Cytosol
Gene Ontology:
Molecular function: nucleic acid binding
Cellular component: nucleus
Genetic constraint (gnomAD): Loss-of-function variants: 29 observed, 28.36 expected, observed/expected ratio (o/e) 1.02, 90% interval 0.76 to 1.39. The synonymous counts are far from expectation, so gnomAD's model fits this gene poorly and the ratio says little. Missense variants: 438 observed, 344.31 expected, observed/expected ratio (o/e) 1.27, 90% interval 1.18 to 1.38. Synonymous variants: 192 observed, 142.39 expected, observed/expected ratio (o/e) 1.35, 90% interval 1.2 to 1.52.
Homologues: Orthologues: macaque R3HDM4 (90% identical), pig R3HDM4 (89% identical), mouse R3hdm4 (84% identical), rat R3hdm4 (84% identical), guinea pig R3HDM4 (84% identical), dog R3HDM4 (60% identical), tropical clawed frog r3hdm4 (56% identical), zebrafish r3hdm4 (49% identical), Caenorhabditis elegans Y46G5A.18 (23% identical).
Diseases named in the same sentence as R3HDM4 in open-access papers:
R3HDM4 is named in the same sentence as 9 diseases in open-access papers, as found by Europe PMC text mining. Sharing a sentence is not in itself a finding about the gene and the disease. The quoted sentences say what the papers report.
acute myeloid leukemia (1 paper, 2025). Acute myeloid leukemia (AML) is a group of neoplasms arising from precursor cells committed to the myeloid cell-line differentiation. "Pan-cancer univariate Cox regression analysis for OS revealed elevated R3HDM4 expression correlated with poor prognosis in multiple malignancies, acting as a risk factor in ACC, KIRC, acute myeloid leukemia (LAML) and LGG, and a protective factor in THYM and UCS." (PMID 41346582, 2025).
diffuse large B-cell lymphoma (1 paper, 2025). "R3HDM4 was only downregulated in diffuse large B-cell lymphoma (DLBC)." (PMID 41346582, 2025).
renal carcinoma (1 paper, 2025). A carcinoma arising from the epithelium of the renal parenchyma or the renal pelvis. "qRT-PCR revealed significantly higher R3HDM4 mRNA levels in renal cancer cell line 786-O than normal renal epithelial cell line HEK-293T." (PMID 41346582, 2025). "Renal cancer cell lines showed variable R3HDM4 expression (high in 786-O; low in KMRC-1), reflecting KIRC molecular diversity and supporting its potential as a subtype-specific malignancy marker." (PMID 41346582, 2025).
renal cell carcinoma (1 paper, 2025). "R3HDM4 expression varied across renal cell carcinoma cell lines: higher in BFTC-909, SLR 26, 786-O, RCC10RGB, KMRC-3, 769-P and lower in KMRC-1, A-704, KMRC-20." (PMID 41346582, 2025).
cancer (1 paper, 2025). A tumor composed of atypical neoplastic, often pleomorphic cells that invade other tissues. "R3HDM4 was a clinically relevant prognostic marker: pan-cancer Cox regression linked its high expression to poor OS in KIRC, LAML, LGG; Kaplan-Meier analysis and time-dependent ROC supported its KIRC prognostic value." (PMID 41346582, 2025). "These scRNA-seq findings position R3HDM4 as a cancer-enriched factor in the KIRC TME, potentially regulating immune infiltration and metastatic potential." (PMID 41346582, 2025). "A G1/S and G2/M phase gene heatmap across cell types demonstrated cell cycle activity primarily in cycling cancer subsets, correlating with R3HDM4 expression and implicating it in proliferative dynamics." (PMID 41346582, 2025). "scRNA-seq revealed R3HDM4’s predominant expression in cancer cell clusters, especially cycling/metastatic subsets, with low expression in immune/stromal cells; unlike bulk RNA-seq averaging signals, scRNA-seq pinpointed its cancer cell-specific pro-tumor effects and indirect TME influence." (PMID 41346582, 2025). "R3HDM4, encoding an R3H domain-containing RNA metabolism protein, is poorly characterized in cancers with no prior KIRC studies." (PMID 41346582, 2025).
R3HDM4 also shares sentences with these, for which no sentence is quoted: adrenocortical carcinoma (1 paper); breast invasive carcinoma (1); glioma (1); tumor (1).